IL1B (interleukin 1 beta)
Diseases named in the same sentence as IL1B in open-access papers (continued):
Sharing a sentence is not in itself a finding about the gene and the disease.
cancer (continued). "IL-1β is a potent inflammatory cytokine affecting dendritic cells (DCs), NK, and T cells, whereas IL-18, with its ability to activate NK and T cells, has shown promise in preclinical cancer immunotherapy studies." (PMID 39737979, 2024). "However, in contrast, any anti-cancer treatments are able to promote IL-1β production by cancer or immune cells, with opposite effects on cancer progression." (PMID 39451257, 2024). "Furthermore, a decreased IL-1β and increased anti-inflammatory cytokine IL-10 levels were also detected after phagocytosis of cancer cells by VISTA+ M2 macrophages." (PMID 38553748, 2024). "IL-1α/IL-1β cytokines promote cancer phenotypes and contribute to resistance in cancer treatment." (PMID 37789138, 2024). "Chia ether significantly minified IL-6 (75.20 ± 0.96 ng/mL) and IL-1β (59.98 ± 2.16 pg/mL) levels more than chia alcohol (80.73 ± 0.73 ng/mL and 61.35 ± 1.63 pg/mL, respectively), compared to the cancer lung control, 67.10 ± 1.72 ng/mL and 69.08 ± 0.83 pg/mL, respectively." (PMID 39338293, 2024). "Recent studies suggest that B cells may serve as effective promoters of metastasis through IL-1β/HIF-2α/Notch1 signaling pathway which stimulate cancer cell migration and invasion." (PMID 38254110, 2024). "Furthermore, the knockdown of FOXO3A inhibited ESCC development and attenuated the pro-cancer effect of overexpressed IL-1β." (PMID 38762529, 2024). "However, prolonged exposure of T cells to IL-1β and/or IL-18 resulted in suppressive effects on T cells and was detrimental to the cancer-bearing organism." (PMID 39796680, 2024). "It is assumed that the level of IL-1β produced, the type of producing cells, the microenvironment (immune cells or fibroblasts), the cancer stage and the anti-cancer therapies used may be involved in the divergent effects of IL-1β." (PMID 38867324, 2024). "The substantial overlap in metabolically regulated genes—such as IL6, IL1B, and COL1A1—in lung epithelial cells associated with PH and all published cancer analyses (where metabolites were elevated) suggests shared mechanisms linking transcriptional changes to genomic alterations." (PMID 39635438, 2024). "As a result, these nsSNPs could lead to a potential dysregulation in the expression of IL1B and inflammatory responses which could contribute to the development and progression of inflammatory diseases and cancers." (PMID 38858637, 2024). "The level of IL-1β depends on both the stage of cancer development and its primary location." (PMID 39519642, 2024). "In addition, CAAs also secrete chemokines and other inflammatory cytokines, such as C-C motif chemokine ligand 2 (CCL2) and IL-1β, to stimulate adipocytes and promote cancer progression." (PMID 39040042, 2024). "Some studies indicate that the involvement of IL-1β in cancer progression and the inhibition of IL-1β could prevent it." (PMID 39769450, 2024). "Another example is canakinumab, a human monoclonal antibody that selectively targets and neutralizes the proinflammatory cytokine interleukin-1 beta (IL-1β), which plays a crucial role in various inflammatory diseases such as autoinflammatory disorders, cardiovascular diseases, and some cancers." (PMID 39390211, 2024). "Additionally, cancer-derived IL-1β also triggers adipocyte transformation and adipose tissue cachexia." (PMID 36672449, 2023). "The investigation of the NLRP3 inflammasome complex is a new horizon to explore, and inhibiting IL-1β or NLRP3 could be a helpful cancer-related therapeutic strategy to improve the existing protocols." (PMID 36902299, 2023). "In the Th1 environment, pro-inflammatory cytokines IL-1α, IL-1β, and IL-6 may participate in cancer eradication by recruiting white blood cells from the circulation and stimulating cells." (PMID 37893233, 2023). "The secretion of IL-1β in fibroblasts could in turn promote the proliferation, migration and invasion of GC cells, so as to promote cancer progression." (PMID 37858201, 2023).
cancer (continued). "A study regarding the TAMs-LIHC interaction ascertained that TAMs could propel the migration of cancer cells by means of stimulating cellular fatty acid oxidation via secreting IL-1β." (PMID 37033261, 2023). "Pro-inflammatory macrophages can kill cancer cells directly, via mechanisms dependent on reactive oxygen species (ROS), reactive nitrogen species, and IL-1β and TNF-α production, or indirectly, through the activation of other immune cells, like cytotoxic T cells and NK cells." (PMID 37686663, 2023). "Since IL-1β is one of the crucial stress-induced cytokines that promote cancer growth and metastasis, its blockers are currently being evaluated in clinical trials for cancer therapy." (PMID 37020461, 2023). "Therefore, in this study, we aimed to elucidate the mechanisms by which IL-1β and TonEBP affect cancer cell migration and invasion." (PMID 38188678, 2023). "Mediators of systemic inflammation, such as nitric oxide, prostaglandins, or cytokines (IL-1β and IL-6), also modify gene expression profile through the activation of DNA methyltransferases (DNMTs) and HDACs, thereby influencing the behavior of cancer cells." (PMID 37190141, 2023). "However, activation of the NLRP3 inflammasome promotes the release of IL-1β, which not only creates a pro-inflammatory environment but also has profound effects on cancer cell proliferation, migration, and metastasis." (PMID 36920652, 2023). "Increased levels of IL-1B mRNA and proteins have been found in various types of cancer." (PMID 37763742, 2023). "Additionally, IL-1B often encourages the growth and invasion of cancer cells as well as neo-angiogenesis and immune cells that infiltrate tumors." (PMID 37894904, 2023). "Interestingly, HNSCCs constitute a tumour environment that promotes Th17 cell activity due to the release of IL-23 and IL-6 by the neoplastic cells themselves and by TIL and IL-1β by immune cells infiltrating the cancer niche." (PMID 36980527, 2023). "IL-1β is a notable biomarker related to muscle wasting in cancer cachexia." (PMID 37755304, 2023). "Hence, VCAN-IKKβ-mediated addiction of KRASMUT cancers to host IL-1β can be used to indirectly target these tumors." (PMID 36980752, 2023). "In addition, isunakinra limited NF-κΒ activation in KrasMUT cancer cells in vivo, a phenomenon we previously showed to be fueled by myeloid IL-1β, as well as their ability for lethal MPE induction." (PMID 36980752, 2023). "Furthermore, targeting the IL-1β/PD-1/PD-L1 pathway can enhance the response to chemotherapy and radiation therapy, indicating its potential as a broad-spectrum cancer therapy." (PMID 37511306, 2023). "An important component of inflammation in our bodies is the inflammasome complex, which converts pro versions of cytokines like IL-1β and IL-18, which aids in cancer progression; thus, investigating various inflammasome inhibitors such as MCC950, CY-09, and others is critical." (PMID 37715239, 2023). "To re-confirm the involvement of IL-1β mediated NF-κB signaling in drug resistance, we designed another experimental set-up where EP and LP cancer cells were exposed to aspirin (ASP; 10 mM), an inhibitor of NF-κB activation and MRP1 was evaluated by flow-cytometry." (PMID 38304256, 2023). "The flavonoid dihydroquercetin, extracted from onions, promotes anti-cancer and anti-inflammatory effects via the induction of apoptosis in cancer cells and the inhibition of pro-inflammatory agents, including NF-kB, TNFα, IL-1β, and IL-6, in LPS-treated cancer and immune cells." (PMID 38140352, 2023). "Moreover, angiopoietin-like 4 (ANGPTL4), a known proangiogenic factor in cancer, is induced by IL-1β from adipocytes in a manner dependent on NF-κB and MAPK." (PMID 36670988, 2023). "However, recent studies have identified IL-1β as a pro-cancer factor due to its immunosuppressive and chemo-resistant properties." (PMID 38026959, 2023). "Recently, IL1B has been shown to induce CXCL8 secretion in human cancer cells." (PMID 37370765, 2023).
cancer (continued). "However, anakinra, an IL-1 receptor antagonist, reduces IL-1β and downstream production of cancer-promoting IL-22." (PMID 36932407, 2023). "Both the HFD and the cancer cells increased the expression of most genes; however, especially Il1b, Ym1, Cxcl2, Cxcl3, and Cxcr2 were among the most responsive genes to both the HFD and the cancer cells in the PSF which were further exacerbated by the combination of the HFD and cancer cells." (PMID 38264656, 2023). "Although nitic oxide (NO), reactive oxygen species (ROS), IL-1β and TNF-α mediated cell death has been studied in cancer cells and may be associated with ICD induction, this cell death mechanism has not yet been elucidated in macrophage mediated cell death." (PMID 38077402, 2023). "In addition, inhibition of NLRP3 inflammasome activity using MCC950 or dampening the downstream effect of IL-1β prevented the proliferation increase in cancer cells." (PMID 37749707, 2023). "To underline, in the BDCs secretome of patients with advanced stage cancer, augmented levels of MGAs along with IL-1β, IL-10 and VEGF were detected, corresponding with the hypoxic, immuno-suppressive and vasculogenic actions respectively, all characteristic of metastatic cancer cells." (PMID 37970208, 2023). "Cancer incidence and mortality were significantly lower for those treated with anti-IL1β versus placebo, suggesting that anti-inflammatory cytokines may have a role in progression and severity of disease." (PMID 37461742, 2023). "Both CCL3 and IL-1β are known to participate in cancer pathogenesis." (PMID 38273861, 2023). "The results demonstrated that IL-1β and IL-6 in Omicron-infected cancer patients were lower than those in non-Omicron-infected cancer patients (P <0.05) and higher than those in Omicron-infected non-cancer-afflicted subjects (P <0.01), respectively." (PMID 37035158, 2023). "IL-1β suppression decreases formation of ROS, AP-1/NF-kB, and cancer cell migration." (PMID 38045808, 2023). "GSDMD-mediated pyroptosis is involved in cancer cell death during chemotherapy and radiotherapy; however, secreted IL-1β may recruit immunosuppressive cell subsets and initiate inflammation-related side effects." (PMID 36932407, 2023). "As a proinflammatory cytokine, IL-1β plays important roles in inflammation and cancer development." (PMID 37443052, 2023). "Furthermore, authors accessed also other prevalent inflammation and cancer cytokines such as IL-1β, IL-2, and IFN-γ, which were overexpressed in TME." (PMID 37958406, 2023). "Moreover, we identified MDSC secreted IL-6/IL-10/IL-1β induced STAT1/STAT3/NF-κβ signaling axis as a targeted cascade to promote early drug resistance in cancer cells." (PMID 38304256, 2023). "Furthermore, dietary cholesterol induces inflammatory responses by increasing IL-1β, a potent cancer-promoting cytokine." (PMID 37543622, 2023). "We examined whether PAK1 signaling participates in the induction of cancer cell migration and invasion by IL-1β." (PMID 38188678, 2023). "CEFs induced cancer cell spreading via IL‐1β secretion, which activates Rac1 in cancer cells." (PMID 34379869, 2022). "The MTT assay was utilized to evaluate the cytotoxicity of CCL21/IL1β on cancer cells." (PMID 36037155, 2022). "However, cancer cell death induced by fractionated low doses of radiation has been shown to decrease iNOS level and NO production, leading to a decrease in IL1β, which favours M2-like macrophages." (PMID 36497148, 2022). "In both primary hepatocytes and cancer cell lines, IL-1β is known as a potent inducer of LCN2." (PMID 35053376, 2022). "Considering the implication of IL-1β in influencing all the initiation-to-progression stages of many tumors and chemoresistance, this cytokine is considered a promising therapeutic target for many types of cancers." (PMID 35530309, 2022). "Interleukin 1 beta (IL-1B) is produced and secreted by immune cells, fibroblasts, or cancer cells." (PMID 35884907, 2022).
cancer (continued). "IL1β has two opposite roles in cancer: promoting cancer and suppressing cancer." (PMID 36132127, 2022). "Intraperitoneal or intrathecal administration of MCC950, a specific NLRP3 inflammasome inhibitor, alleviated mechanical allodynia, and decreased IL-1β and IL-18 release in the lumbar dorsal spinal cord in cancer-induced bone pain and oxaliplatin-induced neuropathy, respectively." (PMID 36324872, 2022). "Recent data suggest that the specific inhibition of IL-1β with a monoclonal antibody could reduce cancer risks." (PMID 35406394, 2022). "Moreover, decreased levels of IFN-γ, GM-CSF, IL-1β, IL-7, IL-12, and IL-13 secretion were seen in cancer patients’ peripheral-blood derived sera when compared to those from the healthy individuals." (PMID 35203349, 2022). "Furthermore, Nlrp3 inflammasome-mediated IL-1β was shown to induce the production of the cancer-promoting cytokine IL-22 by memory CD4+ T cells." (PMID 35517498, 2022). "Moreover, depletion of IL-1β or GM-CSF by shRNA knockdown abrogated the effect of SIRPγ overexpression on reducing sensitivity of cancer cells to phagocytosis." (PMID 35229723, 2022). "Furthermore, the median number of bacterial DNA counts as well as IL-1B levels were significantly higher in patients diagnosed with high grade dysplasia or cancer compared to low grade dysplasia." (PMID 35205769, 2022). "Activation of the NLRP3 inflammasome leads to the release of the proinflammatory cytokines IL-1β and IL-18, which may contribute to cancer development." (PMID 35707534, 2022). "Accumulating evidence suggested the pro-tumoral role of IL1β across a wide range of cancer types." (PMID 35432318, 2022). "In the cancer-induced bone pain model, IL-1β and IL-18 were detected predominantly in neurons." (PMID 36324872, 2022). "Beyond prognosis, IL-1β can also influence anti-cancer treatments." (PMID 36497475, 2022). "In relation to cancer, both a pro- and anti-tumorigenic role for IL-1β has been described." (PMID 36531053, 2022). "Moreover, the overexpression of IL1B in squamocolumnar junctions triggers BE metaplasia/dysplasia to cancer in mouse models." (PMID 35328735, 2022). "Both IL-1α and IL-1β play pro-tumorigenic roles in several cancers." (PMID 35086565, 2022). "Besides its effects on the TME, IL-1β autocrine signaling was shown to act as a direct driver of cancer cell proliferation." (PMID 35517498, 2022). "Inflammasomes regulate the activity of caspase-1 and the maturation of IL1β and IL-18, which act as innate immune system sensors and receptors in various infections, cancer, and other diseases, among which the NLRP3 inflammasome has been well characterized to date." (PMID 35457287, 2022). "Our results imply that conventional cell-based screens for the discovery and development of novel KRAS blockers might be suboptimal, and that IL-1β inhibition may be specifically effective against KRAS-mutant cancers." (PMID 35327394, 2022). "Increases in IL-1β accelerate the growth of cancer cells by inducing immature myeloid cells." (PMID 35681301, 2022). "Moreover, the combined relative abundance of these taxa, a GC microbiome index, significantly correlated with gastric mucosal IL1B expression, which was elevated in the cancer group." (PMID 36501012, 2022). "Similarly, CAFs and adipocytes produce cancer-promoting factors and induce angiogenesis via IL-1β secretion." (PMID 35086565, 2022). "One area of application of such a finding is in cancer chemotherapeutics designed to trigger cell death by activating the apoptosis regulators Bax and Bak, which elicit IL-1β secretion during the late stages of apoptosis, most likely through caspase-3/-7-mediated pannexin-1 cleavage." (PMID 36127465, 2022). "We found similarities in pathways and upstream regulators of FOXO3-deficient macrophages with HFD obese mice colon associated with inflammation (IL-1A, IL-1B, IL-6, IL-8 signaling), growth (ILK signaling, CDK5 signaling, VEGF signaling) and cancer (cAMP-mediated signaling)." (PMID 35323693, 2022).
cancer (continued). "In addition to inducing proliferation and survival of cancer cells, IL-1β can also favor their migration and invasion." (PMID 35517498, 2022). "Our data demonstrate that IL1b may directly upregulate PD-L1 in cancer cells, thus explaining a mechanistic way whereby inflammatory stimulation may favor immune escape while at the same time recruiting additional immune cells through chemokine release." (PMID 35814450, 2022). "Moreover, ATP from dying cancer cells promotes proteolytic maturation of caspase-1 and cleavage and release of interleukin (IL)-1β." (PMID 36212143, 2022). "Furthermore, clinically high levels of inflammatory mediators such as IL-1β and CRP have been demonstrated in several cancer types, including NSCLC, and are frequently associated with detrimental outcomes." (PMID 35739301, 2022). "The expression of several fucosyltransferases involved in Lewis antigen synthesis in gastric cells has been shown to be modulated by the inflammatory cytokines, IL-1b and IL-6, and their prognostic effects on cancer and related motility mechanisms in cancer cells." (PMID 36292744, 2022). "Eight cytokines (IL-1β, IL-6, IL-10, TGF-β, CCL2, CXCL8, CSF-1, and VEGF) were identified to have higher expression values in the high-risk group than in the low-risk group, which was relevant to the progression, invasion, and metastasis of cancers." (PMID 36120553, 2022). "Lewis lung carcinoma (LLC) cancer cells release a high amount of RNAs, which accumulate in the extracellular space and activate epithelial cells, thereby inducing NETosis mediated by proinflammatory cytokines, such as IL1β." (PMID 35574410, 2022). "Hence, ARC confers chemoresistance by controlling the interactions between cancer cells and their microenvironment through an NFκB/IL1β signalling network." (PMID 35954425, 2022). "Therefore, stimulation of C/EBPβ expression by IL-1β during cancer cachexia appears to promote MuSC survival." (PMID 35441960, 2022). "The species B. intestinalis could enhance host immunity by producing metabolites or inducing transcription of interleukin (IL)-1β, and B. xylanisolvens correlated positively with cancer treatment outcomes." (PMID 34970262, 2021). "Recent research demonstrated that reduced NLRP3 inflammasome and IL-1β expression could inhibit the progression of cancer cells." (PMID 34747716, 2021). "The inflammatory processes exacerbated by cytokines TNF-α and IL-1β are key events in IVDD, they contribute to IVDD through degradation of extracellular matrix, and they are implicated in wounds and cancer." (PMID 33579726, 2021). "Overexpression of pro-inflammatory cytokines such as IL-1β and IL-18 may promote cancer progression, increasing an excessive inflammatory response." (PMID 34681768, 2021). "Hence, IL1B-blocking drugs such as anakinra and canakinumab are currently investigated as cancer therapeutics." (PMID 33690729, 2021). "IL-1β is mainly present in the blood circulation and functions within a cascade of cytokines that initiates the inflammatory response and promote the migration of cancer cells." (PMID 34976805, 2021). "Myriad studies have revealed that exposing stromal fibroblasts to cancer-targeted genotoxic agents resulted in significant upregulation of inflammatory factors or cytokines including interleukin (IL)-1β, matrix metalloproteinase-3, IL-6, WNT16B, and IL-813,20,26,29." (PMID 34108603, 2021). "Cancer promotion can be regulated by several pathways associated with inflammation, such as those involving NF-κB, STAT3, mTOR, and MAPKs, which are triggered by pro-inflammatory cytokines like IL-6, TNF-α, and IL-1β." (PMID 34950252, 2021). "However, the ethanolic CN extracts prevented the smoldering inflammation between cancer cells and immune cells by reducing the level of pro-inflammatory cytokines, such as IL-6, IL-1β and TNF-α." (PMID 34379689, 2021).